PKP1 (plakophilin 1)
Diseases named in the same sentence as PKP1 in open-access papers (continued):
Sharing a sentence is not in itself a finding about the gene and the disease.
PKP1 also shares sentences with these, for which no sentence is quoted: esophageal cancer (2 papers); ankylosis (1); cerebral malaria (1); cervical cancer (1); colon cancer (1); cutaneous melanoma (1); ectodermal dysplasia/skin fragility syndrome (1); Fragile skin (1); head and neck cancer (1); head and neck squamous cell carcinoma (1); hereditary disease (1); injury (1); metabolic syndrome (1); non-small cell lung carcinoma (1); Palmoplantar keratoderma (1); panic disorder (1); pharyngeal squamous cell carcinoma (1); skin cancer (1); skin disorder (1).